COL1A1 (collagen type I alpha 1 chain)
Diseases named in the same sentence as COL1A1 in open-access papers (continued):
Sharing a sentence is not in itself a finding about the gene and the disease.
osteoporosis (continued). "The relationship between gene polymorphism of COL1A1 gene and osteoporosis is mostly reported." (PMID 29088884, 2017). "The function of XLOC_013414 is unknown but COL1A1 polymorphisms may individually play minor roles in osteoporosis and fracture." (PMID 28934224, 2017). "Taken together, these analyses revealed that Krm2 expression in osteoblasts has a negative impact on bone integrity, which led us to perform histomorphometry to determine, whether the severe osteoporosis in Col1a1-Krm2 mice is caused by impaired bone formation and/or bone resorption." (PMID 20436912, 2010). "Monogenic forms, often syndromic, were linked to mutations in genes such as COL1A1, COL1A2, and WNT1, whereas multifactorial osteoporosis, particularly postmenopausal, was associated with variants in LRP5, SOST, VDR, and other GWAS-identified loci." (PMID 40772209, 2025). "The immunohistochemistry analysis showed alamandine up-regulated expression of OCN and COL1A1 in bone tissue of OVX-induced osteoporosis rats." (PMID 38200474, 2024). "Consistent with the data from OVX experimental mice, aging (12-month-old)-induced osteoporosis was also delayed in Hif1afl/fl;Col1a1-Cre mice." (PMID 39039245, 2024). "We also took advantage of mice carrying the Col1a1-Krm2 transgene, which display severe osteoporosis." (PMID 35158823, 2022). "First, we established a postmenopausal osteoporosis model in rats by removing ovaries, and measured bone metabolism indexes such as Col1a1, and OST to confirm the therapeutic effect of JG in the treatment of PMOP." (PMID 36386173, 2022). "Three patients with mutations in genes encoding type I collagen (COL1A1 and COL1A2) were identified, and their skeletal abnormalities were characterized primarily by osteoporosis, with less common abnormalities in the limb bones and skull." (PMID 35250876, 2022). "Osteoporosis is also known to be strongly related to the genetic components of type I collagen (COL1A1 and COL1A2)." (PMID 34200258, 2021). "Co-occurrence of COL1A1 and WNT1 mutations was found in a patient with a mild OI phenotype but severe osteoporosis." (PMID 34394176, 2021). "BGLAP and COL1A1 immunohistochemical staining confirmed the decrease in the bone formation marker in osteoporosis patients." (PMID 33006314, 2020). "Concerning organic matrix, COL1A1 gene is implicated in reduced BMD in osteoporosis; in fact, type I collagen polymorphisms (Sp1 and +1245G/T) play a role in development of osteoporosis and fracture." (PMID 33297501, 2020). "In the past, research has mainly focused on few candidate genes, namely the VDR, estrogen receptor alpha (ER-α) and COL1A1 genes, which have been investigated with regard to response to osteoporosis-drugs." (PMID 33162933, 2020). "Previous studies have shown associations between Col1A1 Sp1 polymorphisms and low BMD, osteoporosis, and increased fracture risk, while some have not reached statistical significance." (PMID 30251958, 2019). "The present reports on COL1A1 have focused mainly on bone diseases, tumor tissues, osteoporosis, and esteogenesis." (PMID 31072014, 2019). "So far, more than 800 mutations have been reported only for COL1A1, mainly associated with skeletal and dermatological conditions such as OI, Ehlers-Danlos syndrome (EDS), bone mineral density variation, osteoporosis and Caffey disease." (PMID 27484908, 2016). "SPP1 signalling and COL1A1 signalling in osteoporosis were previously reported; and NT5E, HTRA1 and ANGPT1 signalling pathways reported here require further confirmation." (PMID 27690016, 2016). "Lrp 5 deficiency (Lrp5−/−) as well as osteoblast-specific overexpression of Krm2 in mice (Col1a1-Krm2) result in severe osteoporosis occurring at young age." (PMID 25061805, 2014). "The expressions of IL17RC, COL1A1, and ESR1 in bone marrow mesenchymal cell are expected to be used in developing biomarkers for detecting osteoporosis and for screening osteoporosis risk groups." (PMID 23731710, 2013).
osteoporosis (continued). "We identified enhanced expression of 39 genes in hMSC-OP and reduced expression of 16 genes that are already described as reliable or promising candidates for osteoporosis, including susceptibility genes like LRP5, SPP1 (Osteopontin), COL1A1 and SOST." (PMID 23028809, 2012). "When we performed non-decalcified histology of vertebral body sections, we observed that female Col1a1-Krm2 transgenic mice progressively develop severe osteoporosis." (PMID 20436912, 2010). "Here we show that Kremen-2 (Krm2) is predominantly expressed in bone, and that its osteoblast-specific over-expression in transgenic mice (Col1a1-Krm2) results in severe osteoporosis." (PMID 20436912, 2010). "Polymorphisms in COL1A1 (collagen type I alpha 1) and VDR (vitamin D receptor), implicated in osteoporosis among beta-thalassemia major (β-TM) patients, may also predispose beta-thalassemia minor (βTT) carriers to skeletal fragility." (PMID 40932695, 2025). "While previous research has identified COL1A1 rs1800012 as a risk factor for osteoporosis, its age-specific effects have not been well documented." (PMID 40507792, 2025). "To directly test the role of osteoblast Gpx4 suppression in ferroptotic osteoporosis, we generated a strain of osteoblast-specific Gpx4 knockout mice by crossing Gpx4fl/fl mice with Col1a1-Cre mice, supposedly resulting in the deletion of exons 2–4 of the Gpx4 gene in osteoblasts." (PMID 39617773, 2024). "Specific genetic associations of collagens may indicate an increased incidence of healthier aging, in which COL1A1 rs107946 may suggest accelerated osteoporotic-related aging, but COL1A2 rs3917 suggests a reduced risk of osteoporosis." (PMID 37189830, 2023). "Because osteoporosis is a systemic disease and is strongly related to genetic components of type 1 collagen (COL1A1 and COL1A2), we propose that osteoporotic conditions may influence cancellous bone of the skull." (PMID 33071940, 2020). "Furthermore, the generally acidic osteoporotic bone in untreated osteoporosis could support bone metastasis with the secretion of proteins such as COL1A1, COL4A2, NID1, FBLN1, and NRP2." (PMID 35159353, 2022). "Therefore, COL1A1 may be involved in the pathogenesis of osteoporosis and atherosclerosis by influencing bone formation, vascular fibrosis, immune response, but these related molecular mechanisms warrant additional investigation." (PMID 35937806, 2022). "The expression pattern of IL17RC, COL1A1, and ESR1 can be useful in osteoporosis detection, which may help in identifying those populations at high risk for osteoporosis, and in directing treatment of osteoporosis." (PMID 23731710, 2013). "Recent studies have reported abnormal expression of COL1A1 and COL1A2 in osteogenesis, osteoporosis, various bone disorders, and multiple cancers." (PMID 41463322, 2025). "By clustering annotation of human osteoporosis single-cell datasets, we manually annotated only the osteoclast clusters using markers CDH11 and COL1A1, dividing the data into osteoclast and non-osteoclast clusters." (PMID 38883609, 2024). "Especially COL1A1, the major organic component of bone matrix and OGN, which was found to be downregulated in senile osteoporosis, was significantly higher expressed in osteogenically treated JPCs without dexa." (PMID 36393863, 2022). "(A) COL1A1 and BGLAP immunohistochemical staining of the femur head from hip dysplasia and osteoporosis patients." (PMID 33006314, 2020). "Secreted phosphoprotein 1 (SPP1), collagen type I α 1 chain (COL1A1), 5′-nucleotidase ecto (NT5E), HtrA serine peptidase 1 (HTRA1) and angiopoietin 1 (ANGPT1) and their signalling pathways are shown to be involved in osteoporosis in CD patients." (PMID 27690016, 2016). "By the comparison of gene chips from five osteoporosis patients and four normal samples of bone marrow stem cell, we identified genes (IL17RC, COL1A1, and ESR1) that directly interact with the OPG gene." (PMID 23731710, 2013).
osteoporosis (continued). "Then, six hub genes (COL1A1, IBSP, CTSD, RAC2, MAF, and THBS1) were obtained through the integration of multisource databases and they were all significantly upregulated in both the osteoporosis and atherosclerosis group compared with the control group." (PMID 35937806, 2022). "Elevated SPP1, COL1A1 and NT5E proteins may be secreted from the pituitary tumor to directly target the skeletal system, with resultant osteoporosis, while downregulated HTRA1 and ANGPT1 may deregulate in bone formation and development." (PMID 27690016, 2016). "SPP1 (secreted phosphoprotein 1), COL1A1 (collagen type I α 1 chain), NT5E (5′-nucleotidase ecto), HTRA1 (HtrA serine peptidase 1) and ANGPT1 (angiopoietin 1) and their signalling pathways involving osteoporosis in CD patients are identified." (PMID 27690016, 2016). "More cases were required for the remaining six gene loci, namely, ESR1 PvuII (rs2234693), VDR ApaI (rs7975232), VDR BsmI (rs1544410), COL1A1 1997GT (rs1107946), ESR1 G2014A (rs2228480), and ESR2 AluI (rs4986938), before a definite conclusion could be made on their correlation with osteoporosis." (PMID 35452412, 2022). "The sample sizes for four gene loci, namely, COL1A1 1245GT (rs1800012), IGF1 (rs5742612), IL6 G174C (rs1800795), and ESR1 XbaI (rs9340799), were sufficient for a conclusion of noncorrelation with osteoporosis." (PMID 35452412, 2022).
renal fibrosis (55 papers, 2014 to 2026). A final common manifestation of a wide variety of chronic kidney diseases characterized by glomerulosclerosis and tubulointerstitial fibrosis. "HY7718 supplementation was associated with reduced expression of genes related to renal fibrosis (Col1a1, Acta2) and vascular inflammation (Icam-1, Vcam-1)." (PMID 42196327, 2026). "Characterised by deposition of extracellular matrix, such as collagen type I alpha 1 chain (COL1A1) and fibronectin (FN), renal fibrosis causes tissue scarring and ultimately leads to end‐stage renal disease." (PMID 37933774, 2023). "It caused both tubular cell death and renal fibrosis, as indicated by Sirius red and collagen type 1 alpha 1 (COL1A1) staining." (PMID 35482420, 2022). "Last, the lesser inflammation was associated with lower renal fibrosis and expression of profibrotic genes (Col1a1, Col3a1, Fn1, and Vim) in UUO kidney of Casp9 HZ mice." (PMID 34739325, 2021). "Confirming our dose range experiments, X203 reduced AKI-induced loss of kidney mass, limited renal fibrosis, and improved renal function while lowering inflammatory (Tnfα, Il6, Ccl2, Ccl5, Il1β), fibrosis (Col1a1, Col1a2, Col3a1, Fn1, Acta2) and tubular damage (Kim1, Ngal) markers." (PMID 36470928, 2022). "Upregulation of FSP1, Col1a1, and Vim has been implicated in renal fibrosis and the downregulation of the antifibrotic BMP4 and BMP7 confirmed the fibrosis establishment, while central role of TGF-β in human and experimental models for renal fibrosis has been well described." (PMID 24995284, 2014). "Western blotting confirmed the upregulation of fibrosis-related proteins such as TGFβ, α-SMA, and Col1a1, further supporting the presence of renal fibrosis." (PMID 40661082, 2025). "In accordance with this study, recent studies have also found that ADSC treatment significantly reduces renal fibrosis and reduces renal levels of mRNA COL1A1, TGFB1, CTGF, and ACTA2." (PMID 39309193, 2024). "L002, a FATP300 inhibitor, attenuates renal fibrosis by inhibiting H4 acetylation, thereby reducing the expression of COL1A1 and COL4A3." (PMID 38929505, 2024). "Q-PCR indicated a significant reduction in the expression of renal fibrosis-related genes (fn-1, αSMA, Col1a1, Col3a1, Ctgf, fsp1, KIM) and inflammatory cytokines (Tgfα, Tgfβ, Il-1b, Il-4, Il-6, CD44, CD68) in the kidney of the acetate-treatment group." (PMID 36922584, 2023). "Meanwhile, the expression levels of COL1A1, α‐SMA and FN in VHL−KO; Setd2−KO mice were much higher than that in VHL−KO mice, suggesting that SETD2 deficiency leads to renal fibrosis." (PMID 37933774, 2023). "In a rat model of hypertensive cardiorenal disease, FIN also attenuated renal fibrosis and reduced the production of pro-fibrotic collagen type I α 1 chain (COL1A1) in the kidney." (PMID 38174337, 2023). "Masson and Col1A1-IF staining confirmed that BT424 treatment reduced renal fibrosis in the UUO kidneys." (PMID 37463911, 2023). "Renal fibrosis markers, col1a1 and fibronectin, were highly expressed in the WT UUO group but were significantly suppressed in the Sult1a1-KO UUO group." (PMID 37511089, 2023). "At the same time, expression of inflammatory cytokines (Il1b, Csf2, Tnfa, and Cxcl10), renal fibrosis, and profibrotic genes (Col1a1, Col3a1, Fn1, and Vim) was lower in the FA-treated Casp9 HZ mice." (PMID 34739325, 2021). "Forced expression of NFAT2 by RV230-NFAT2 further exacerbated renal fibrosis, reflected by increased protein expression of COL1a1 and α-SMA." (PMID 34707090, 2021). "We measured the expression of renal fibrosis markers α-Sma, Tgf-β and Col1a1 in CON ASO- and DDR2 ASO-treated AS mice." (PMID 33706638, 2021). "One major component of this matrix is Collagen I, which excessively accumulates in renal fibrosis, wherefore the expression of Col1a1 was crucial to investigate." (PMID 32059667, 2020).
renal fibrosis (continued). "Ureter obstruction resulted in a large increase in renal fibrosis and macrophage infiltration markers (TGFβ1, COL1A1, and F4/80), which were unaffected by either CD40 activation or in CD40 knockout mice." (PMID 26623936, 2015). "Moreover, AZ505 inhibited the expression of α-SMA, COL1A1, and FN, thereby suppressing renal fibrosis." (PMID 39457592, 2024). "The mRNA levels of α-SMA, Col1a1, Col3a1, and Postn were also reduced in the c-AblMyo−cKO mice, demonstrating that specific knockout of c-Abl in myofibroblasts effectively alleviated established renal fibrosis." (PMID 38689280, 2024). "Additionally, pathological collagen deposition is a hallmark of renal fibrosis, and we found that PGE2 treatment inhibited the expression of Col1a1 in Sox9+ cells and kidneys after AKI, which was further confirmed by Masson trichrome staining." (PMID 38801100, 2024). "Renal fibrosis was measured on day 7 with Sirius red histology and COL1A1 IHC." (PMID 35482420, 2022). "In addition, SR decoction has a therapeutic effect on renal fibrosis by partly reversing the expression changes of major biomarkers in the kidney, such as E-Cadherin, Col1a1, and Fibronectin." (PMID 35392552, 2022). "Next, renal fibrosis markers were assessed, including COL1A1, VIM, CDH1, and ACTA2." (PMID 32854194, 2020). "Furthermore, renal gene expression representing markers of renal fibrosis and inflammation, such as COL1A1, COL1A3, TIMP1 and TGF-β, are significantly increased in 5/6 Nx rats compared to 5/6 Nx mice." (PMID 32099009, 2020). "In addition, YB-1 was demonstrated to attenuate fibrosis through direct binding onto the Col1a1 promoter in a renal fibrosis model." (PMID 31588235, 2019). "However, the expression of ECM genes such as mesenchymal collagens Col3a1 and Col1a1 as well as EMT markers found in tumorigenic EMT or renal fibrosis, including EMT-associated cytoskeleton Vimentin, Fn1 and Sparc, were significantly increased in Smarca4cKO tubular cells." (PMID 37727504, 2023). "Biologically, 1-5 exhibited varying degrees of inhibitory activity against renal fibrosis, as evidenced by the downregulation of the key fibrotic markers α-smooth muscle actin (α-SMA) and collagen I (COL1A1)." (PMID 41892980, 2026). "It significantly reduced cardiac and renal fibrosis and suppressed the expression of pro-inflammatory (IL-1β, TNF-α), pro-fibrotic (Col1A1, α-SMA), and cardiac stress (BNP, ET-1, ANF) markers." (PMID 41596359, 2026). "Western blotting confirmed the downregulation of fibrosis-related proteins such as TGFβ, α-SMA, and Col1a1, further supporting the therapeutic effects of BBR on renal fibrosis." (PMID 40661082, 2025). "We also demonstrated that renal fibrosis was attenuated by PRDM16 overexpression, as the mRNA levels of Col1a1, Col3a, Fibronectin, and Vimentin, the protein levels of Fibronectin and α-SMA, and collagen deposition decreased." (PMID 40758676, 2025). "To further evaluate the effect of ZLN005 on UUO-induced renal fibrosis, we analyzed the expression of several fibrosis biomarkers, including Fibronectin, α-SMA and COL1A1." (PMID 35455432, 2022). "Quantitative PCR indicated a significant increase in the expression of renal fibrosis-related genes such as TGF-β1 (Transforming Growth Factor beta 1) and Col1a1 (collagen alpha-1 type 1) in the kidney of the CKD mice compared to control mice." (PMID 36460743, 2022). "In the study, SR decoction reduced the mRNA levels of Col1a1 and Fibronectin in kidney tissues of CRF mice, implying its efficacy in the treatment of renal fibrosis." (PMID 35392552, 2022). "Our results indicate that renal fibrosis and RAS‐related genes (Fn, a‐SMA, Col1a1 and Col4a1) are increased at mRNA and protein expression levels in 5‐month‐old miR‐TKO mice." (PMID 34197043, 2021). "Inhibited expression of Col1a1, fibronectin, and α-SMA expression hinder renal fibrosis in UUO mice and NIH 3T3 fibroblasts." (PMID 32092824, 2020).